FOXM1 (forkhead box M1)
Diseases named in the same sentence as FOXM1 in open-access papers (continued):
Sharing a sentence is not in itself a finding about the gene and the disease.
breast cancer (continued). "In breast cancer FOXM1 expression is linked with estrogen receptor (ERα) activity and resistance to endocrine therapies, with high levels correlated with poor prognosis." (PMID 23347430, 2013). "As FOXM1 has been implicated as an important transcription factor in breast cancer, we mapped FOXM1 binding genome-wide using ChIP-seq in asynchronous MCF7 cells to determine the regulatory regions bound by FOXM1." (PMID 23347430, 2013). "Breast cancer is one of the leading causes of cancer mortality in women and numerous studies have shown a correlation between FOXM1 expression and breast cancer progression, suggesting that FOXM1 is a potential prognostic breast tumor marker." (PMID 23347430, 2013). "FOXM1 over-expression has also been linked with drug resistance in breast cancer chemotherapy and therefore poor clinical prognosis." (PMID 23347430, 2013). "Reginato’s group first demonstrated negative regulation of MMP2 expression upon OGT inhibition using OGT shRNA in breast cancer cells (an effect probably mediated by down-regulation of FOXM1 protein), associated with decreased cell invasiveness." (PMID 23964270, 2013). "Among the Fox proteins, accumulating evidence has associated FoxM1 overexpression with a wide range of cancers, including breast cancer, colorectal cancer, lung, medulloblastoma, glioblastoma, pancreatic cancer and leukemia." (PMID 23110199, 2012). "Targeting 14-3-3ζ and its coregulated proteins, such as FOXM1, should prove valuable in restoring endocrine sensitivity and reducing risk of breast cancer recurrence." (PMID 21707964, 2011). "Since FOXM1 has been associated with a network of genes, it is crucial to investigate how its dysregulation can promote these cellular changes that can eventually lead to different types of cancer, including breast cancer." (PMID 38886738, 2024). "Moreover, increased expression of FOXM1 has been associated with a poor prognosis for patients with breast cancer, aligning with our results of bioinformatics." (PMID 38978058, 2024). "In addition, compared to normal breast tissue and tumor tissues, FOXM1 is associated with ER expression in breast cancer, resistance to hormone therapy, and poor prognosis." (PMID 39594778, 2024). "Transcriptional enrichment analysis revealed that MRPS30‐DT might be associated the most with ZNF217 and FoxM1, whose roles in breast cancer have been demonstrated in the literature." (PMID 38886335, 2024). "Resistance to cell death is a hallmark of cancer, and our studies reveal that in breast cancer cells that acquire resistance to the growth suppressive effects of FOXM1 inhibitor, cell survival is associated with marked changes in modulators of ferroptosis and autophagy that enable cell viability." (PMID 38980505, 2024). "FOXM1 has been implicated in estrogen signaling in ER+ BC cells, in which FOXM1 is a transcriptional target of ERα and plays a critical role in the sensitivity and resistance to endocrine (anti-estrogen) therapy in breast cancer." (PMID 39594778, 2024). "The FOXM1 gene has been reported to overexpress in aggressive, therapy-resistant variants of hormone receptor-positive and triple-negative breast tumors and correlated with a poor prognosis in a variety of cancers, such as breast cancer and colorectal cancer." (PMID 37607964, 2023). "Furthermore, aberrant upregulation of FoxM1 has been implicated in tumorigenesis and tumor progression of breast cancer." (PMID 35884976, 2022). "We found overexpression of KIF23 could partly reverse the decrease in breast cancer cells proliferation caused by the knockdown of FOXM1." (PMID 35524313, 2022). "Consistent with this hypothesis, using Tissue Microarray sections of breast cancer samples, we confirmed that elevated eIF4E expression was significantly associated with ERα and FOXM1 protein expression as well as with tamoxifen resistance." (PMID 32066877, 2020). "FOXM1 has been implicated in breast cancer CSC phenotype and TNBC/basal-like BC biology." (PMID 30572639, 2018).
breast cancer (continued). "FoxM1 plays diverse roles in different molecular subtypes of breast cancer, which might be underlying the diverse mechanism of tumorigenesis and genetic background, as well as orchestrating with other cofactors in various tumor contexts." (PMID 29416660, 2018). "Thus, in the present study, the antitumor mechanism of Moracin D was elucidated in breast cancer cells in association with FOXM1 and β-Catenin/GSK3β signaling with the possibility of a potent pharmaceutical for future agricultural commercialization." (PMID 30201862, 2018). "Treatment of ER+ breast cancer cells also led to a senescence response as indicated by accumulation of β-galactosidase, formation of senescence-associated heterochromatin foci, and a decrease in FOXM1 positive cells." (PMID 29050219, 2017). "One plausible explanation is that estrogen receptor alpha (ERα), which is present in MCF7 but not in MDA-MB-231 cells, modulates FOXM1 activity by recruiting FOXM1 to ERα binding sites and causing differential FOXM1 binding between the two breast-cancer cell lines." (PMID 29100329, 2017). "The FOXM1 transcription factor is a key regulator of various biological processes, such as DNA replication and repair and cell cycle progression, and plays an important causal role in the development of aggressive breast cancer." (PMID 28280740, 2017). "FOXM1 caused doxorubicin resistance in breast cancer by enhancing DNA repair." (PMID 26942015, 2016). "FOXM1 is a transcription factor implicated in mitosis, a component of the 54-gene mitotic network, and a known transcriptional target of estrogen receptor alpha, with an important role in breast cancer endocrine biology." (PMID 27368372, 2016). "FOXM1 has been implicated in mediating drug resistance in breast cancer by enhancing DNA repair." (PMID 26588055, 2016). "MYC and FOXM1 have been previously associated with breast cancer growth." (PMID 26894864, 2016). "Indeed, our analysis showed that FOXM1 is highly expressed in multiple cancers and associated with bad prognosis in breast cancer." (PMID 24342878, 2013). "Furthermore, consistent with our findings, a recent study has shown that upregulation of FOXM1 cells confer cisplatin resistance in breast cancer cells through deregulation of the DNA repair pathway causing genomic instability." (PMID 20187950, 2010). "Interestingly, both miR-4521 overexpressing and FOXM1 inhibitor thiostrepton treated cells showed foci formation prior to DOX treatment suggesting their susceptibility to ROS induced DNA damage due to decreased FOXM1 expression and impaired DNA repair activity in breast cancer cells." (PMID 37025658, 2023). "Even more, the expression and prognostic value of FoxM1 in BC patients were highly associated with molecular subtypes and expressions of ER/PR, which imply the potentiality of FoxM1 acting as a master gene with important functions in breast cancer." (PMID 29416660, 2018). "Our findings reveal that TAM resistance is associated with upregulation of FOXM1 and with a FOXM1-dependent gene expression program that enhances cell proliferation and invasiveness and elicits an increase in the proportion of CSCs within the breast cancer cell population." (PMID 25213081, 2014). "This study investigated the time-dependent expression of miR-548c-3p and its post-transcriptional regulation of E2F3 and FOXM1 in MCF-7 breast cancer cells." (PMID 41596697, 2026). "As expected, the majority of the target genes were significantly increased in breast tumors, which is highly consistent with the global up-regulation of FOXM1 in breast cancer." (PMID 41584858, 2026). "As the most up-regulated gene in breast cancers, FOXM1 is specifically highly expressed in the cycling myeloid cells." (PMID 41584858, 2026). "TCGA-based analyses confirmed overexpression and hypomethylation of E2F3 and FOXM1 in breast cancer, particularly in triple-negative tumors, and high expression of both genes was associated with poor survival." (PMID 41596697, 2026).
breast cancer (continued). "As the upstream gene of FOXM1, miRNA-4521 directly targets FOXM1 in breast cancer cells and inhibits its expression, inducing cell cycle arrest, DNA damage, and cell death." (PMID 40003882, 2025). "FOXM1 is responsible for the maintenance of BCSCs stemness and promotion of breast cancer progression." (PMID 40003882, 2025). "Dihydroartemisinin and JKE1674 work synergistically with FOXM1 inhibitors to reduce breast cancer cell viability, induce ferroptosis, and overcome FOXM1 inhibitor resistance." (PMID 40143112, 2025). "During the progression of breast cancer, various dysregulated factors target FOXM1 and eventually induce the deterioration of the cancer." (PMID 40003882, 2025). "FoxM1 is aberrantly expressed in cells of several breast cancer subtypes and can affect cell cycle progression by modulating cell cycle-related genes." (PMID 40672756, 2025). "Our study revealed strong positive correlations between KPNA2 and FOXM1, CCNB1, and CCNB2 expression, with a significant association with the G2/M checkpoint pathway in breast cancer patients." (PMID 40002266, 2025). "Consistently, ERK/CDK4/6 drug perturbation in E/M cells suppressed FOXC2/p63, FOXM1, self-renewal, organoid formation and mammary tumour growth via epithelial differentiation." (PMID 40764669, 2025). "The interplay between FOXM1 and ERα plays a crucial role in breast cancer development and treatment response." (PMID 40002266, 2025). "When breast cancer cells become resistant to FOXM1 inhibitors, ferroptosis-related signaling pathways are changed." (PMID 40143112, 2025). "FOXM1 also serves as a molecular partner of HMGA1 in breast cancer progression: HMGA1 binds to FOXM1 and increases its activity as a promotor of Vascular Endothelial Growth Factor (VEGFA)." (PMID 40003882, 2025). "Except for targeting G2/M phase genes to promote breast cancer cell proliferation, FOXM1 transactive c-Src forms a positive feedback loop that leads to uncontrolled proliferation and breast cancer." (PMID 40003882, 2025). "This is the first paper that demonstrates high KPNA2/low FOXM1 predicts better survival in HR+/HER2- breast cancer." (PMID 40002266, 2025). "In conclusion, the findings suggest that KPNA2 and FOXM1 play a crucial role in breast cancer progression by positively correlating with key genes involved in cell cycle regulation and molecular subtypes." (PMID 40002266, 2025). "In breast cancer, studies show that FOXM1 directly regulates KPNA2 as a target gene, while KPNA2 reciprocally facilitates FOXM1’s nuclear transport, creating a regulatory loop that influences tumor progression." (PMID 40002266, 2025). "We validated this finding by inhibiting FOXM1 in breast cancer cell lines with three different small-molecule FOXM1 inhibitors, and we observed reduced cell motility." (PMID 40588571, 2025). "A previous study has shown that YTHDF1 facilitates the translation of m6A-modified FOXM1 to enhance breast cancer metastasis." (PMID 40568348, 2025). "In the present study, UBE2C was found to be markedly upregulated in breast cancer and transcriptionally regulated by FOXM1." (PMID 40729680, 2025). "FOXM1, an oncogenic transcription factor in breast cancer, regulates critical cell cycle transitions and DNA repair processes." (PMID 40002266, 2025). "In the present study, UBE2C was significantly upregulated in breast cancer and was transcriptionally regulated by FOXM1." (PMID 40729680, 2025). "Researchers have also discovered many other miRNAs that are regulated by FOXM1 and play crucial roles in important pathways in breast cancer, such as miR-21, miR-30a, and miR-95." (PMID 40003882, 2025). "In breast cancer, Forkhead box M1 (FOXM1) has been identified as a biomarker of resistance to PI3Kα inhibitors." (PMID 41152975, 2025).
breast cancer (continued). "For example, the targeted nanoparticle system for FOXM1 condensates in breast cancer regulates molecular hydrophobicity to break through the physical barriers and achieve a therapeutically effective local drug concentration within the condensates." (PMID 41323740, 2025). "The observation that ERα-positive breast cancer cells express elevated levels of FOXM1 protein suggests that FOXM1 expression is regulated by ERα, highlighting the importance of understanding FOXM1’s role in endocrine sensitivity and resistance." (PMID 40002266, 2025). "In the study, UBE2C was found to be significantly overexpressed in breast cancer and transcriptionally regulated by FOXM1." (PMID 40729680, 2025). "Studies have confirmed that phosphorylation is one of the most common modifications occurring in breast cancer that determines the activation state, cellular localization, and stability of FOXM1." (PMID 40003882, 2025). "FOXM1 is a key mediator of mitogenic functions of ERα and estrogen in breast cancer cells, which plays a pivotal role in promoting cell survival and resistance to endocrine therapies." (PMID 40720499, 2025). "Hyperactivated ARID1A/phospho-HDAC6/FOXM1 forms similar condensates in Ewing’s sarcoma or breast cancer recruiting BAFs complexes, Pol II, and coactivators to remodel chromatin structure that drive oncogenic transcription and tumor progression." (PMID 40507965, 2025). "Another EMT pathway, Wnt/β-Catenin, is also the common mechanism for FOXC1, FOXF2, and FOXM1 to regulate breast cancer EMT." (PMID 40003882, 2025). "One study proposed the possibility of cooperation among several FOX TFs: FOXA1 first turns on chromatin in breast cancer, allowing nearby ER α binding, and then FOXM1 can replace FOXA1 and activate cell cycle genes." (PMID 40003882, 2025). "So, the FOXM1-induced overexpression of slug confers invasive phenotypes to breast cancer cells and stimulates EMT." (PMID 40003882, 2025). "Two thiazole antibiotics including Siomycin A and thiostrepton displayed their ability to inhibit FOXM1 in transformed lung fibroblast and breast cancer cell line models." (PMID 40630538, 2025). "For instance, in breast cancer, PSMD14 removes K63-linked ubiquitin chains from FOXM1 to activate the PI3K/AKT/mTOR pathway, thereby facilitating malignant progression." (PMID 41488674, 2025). "Taken together, these results indicated that FOXM1 transcriptionally regulated the expression of UBE2C in breast cancer cells." (PMID 40729680, 2025). "Studies have shown that FOXM1 regulates ERα expression in breast cancer cells, and its target cyclin D1 correlates with ERα positivity." (PMID 40002266, 2025). "Our study investigated the prognostic significance of FOXM1 expression specifically in HR+HER2- breast cancer patients with high KPNA2 levels." (PMID 40002266, 2025). "The proliferation-specific oncogenic transcription factor, FOXM1 is overexpressed in primary and recurrent breast tumors across all breast cancer (BC) subtypes." (PMID 39762471, 2025). "New inhibitors of FOXM1 have been highlighted as an attractive target for controlling drug-resistant and difficult-to-treat breast cancers." (PMID 39834541, 2024). "FOXM1 shows distinct patterns of expression in different breast cancer subtypes and is seen as a promising candidate target in breast cancer treatment." (PMID 39530738, 2024). "Some of these miRNAs, such as miR34a and miR-877-5p, are reduced or lost in various cancers such as breast cancer, liver cancer, cervical cancer, stomach cancer, and lung cancer, potentially leading to overexpression of FOXM1." (PMID 39594778, 2024). "Specifically, USP39 promotes breast cancer cell proliferation and tumor growth by deubiquitinating and stabilizing the transcription factor FOXM1." (PMID 39695108, 2024).
breast cancer (continued). "We also describe changes that occur when breast cancer cells become resistant to the anticancer actions of the FOXM1 inhibitors." (PMID 38980505, 2024). "Taken together, these data suggested that CDCA5 facilitated malignant behaviors of breast cancer cells via promoting the binding of E2F1 to FOXM1 promoter." (PMID 38978058, 2024). "Our results revealed the expression levels of FOXA1 and FOXM1 were significantly higher in breast cancer tissues than in normal tissues." (PMID 38608123, 2024). "For example, According to one study, DNMT1-mediated FOXO3a promoter hypermethylation reduces FOXO3a expression in breast cancer, and FOXO3a decreases breast cancer stem cell characteristics and tumorigenicity through lowering FOXM1/SOX2 signaling." (PMID 38436027, 2024). "FOXM1 is overexpressed in different subtypes of breast cancer including TNBC, and is necessary for mitotic progression and maintenance of chromosome stability." (PMID 38886738, 2024). "Representative pictures of both mice and tumor tissues indicated that FOXM1 knockdown impaired tumor growth of breast cancer cells induced by CDCA5 in vivo, which was validated by results of tumor weight." (PMID 38978058, 2024). "Analysis of microarray data using the KM Plotter tool showed that overexpression of ATAD2, E2F1, and FOXM1, each conferred significantly poorer recurrence-free survival in breast cancer patients." (PMID 39335162, 2024). "FOXM1 expression is associated with an advanced tumor stage, high proliferation rate, and poor prognosis, suggesting that FOXM1 is a new prognostic marker for patients with breast cancer." (PMID 39594778, 2024). "In the current work, we examine the role of FOXM1 in promoting breast cancer cell survival and aggressiveness, and we provide information delineating how these FOXM1 inhibitors suppress FOXM1 activities in cells sensitive to them." (PMID 38980505, 2024). "HMGA1 promotes breast cancer angiogenesis by supporting the stability, nuclear localization, and transcriptional activity of FOXM1." (PMID 39040191, 2024). "For example, there is an increase in FOXM1 expression in breast cancer, hepatocellular carcinoma, and basal cell carcinoma." (PMID 38794221, 2024). "The overexpression of FOXM1 in breast cancer cells partially offset the tumor suppressor impact of YTHDF1 silencing." (PMID 39342406, 2024). "Together with its role as breast cancer oncogene involved in therapy resistance, these data imply FOXM1 as a viable candidate inducing DUSP6 expression during the DTP-DTEP transition." (PMID 38886591, 2024). "In breast cancer, and many other cancers, the oncogenic transcription factor FOXM1 is often upregulated and overexpressed, whereas it is absent or present at only very low levels in most normal adult tissues." (PMID 38980505, 2024). "We reported previously that inhibition of FOXM1 dramatically reduced breast cancer proliferation and increased apoptosis, effectively blocking the pro-tumorigenic and pro-metastatic actions of FOXM1." (PMID 38980505, 2024). "In breast cancer, FOXM1 has been observed at elevated levels and is known to promote breast cancer cell stemness and migration in a YAP1-dependent manner." (PMID 38978058, 2024). "This ability of FOXM1 to aid and promote tumorigenesis and metastasis has been studied in ovarian carcinoma, breast cancer, and non-small cell lung cancer as well." (PMID 39272919, 2024). "All together, we demonstrated that CDCA5 facilitated cell proliferation and migration, inhibited cell apoptosis via targeting FOXM1 in breast cancer." (PMID 38978058, 2024). "Both drugs inhibited cell proliferation and FOXM1 protein in breast cancer cell lines in a dose-dependent manner, with rabeprazole being more potent compared to pantoprazole." (PMID 38918225, 2024). "Our current study provides the first evidence that Rabeprazole and Pantoprazole can bind to FOXM1 and inhibit its activity and downstream signaling, including eEF2K and pEF2, in breast cancer cells." (PMID 38918225, 2024).